ATXN1L (ataxin 1 like)
Description:
Chromatin-binding factor that repress Notch signaling in the absence of Notch intracellular domain by acting as a CBF1 corepressor. Binds to the HEY promoter and might assist, along with NCOR2, RBPJ-mediated repression. Can suppress ATXN1 cytotoxicity in spinocerebellar ataxia type 1 (SCA1). In concert with CIC and ATXN1, involved in brain development (By similarity).
Synonyms: BOAT; BOAT1
Tractability: PROTAC: ubiquitination databases record sites on it; its protein half-life has been measured.
Gene: Protein-coding gene on chromosome 16 (71,808,439 to 71,885,268, forward strand). Ensembl gene ENSG00000224470.
Subcellular location: Nucleus; Cell projection, dendrite
Subcellular location (Human Protein Atlas): Nucleoplasm; Nucleoli
Gene Ontology:
Molecular function: protein binding; chromatin binding; RNA binding; POZ domain binding
Biological process: brain development; learning; memory; negative regulation of transcription by RNA polymerase II; social behavior; regulation of DNA-templated transcription
Cellular component: nucleolus; nucleoplasm; nucleus; dendrite
Genetic constraint (gnomAD): Loss-of-function variants: 8 observed, 41.69 expected, observed/expected ratio (o/e) 0.19, 90% interval 0.11 to 0.35. The upper end of that interval is the gene's LOEUF score, 0.35, which puts it in group 1 of 6, group 1 being the genes least tolerant of losing a copy. Missense variants: 856 observed, 897.39 expected, observed/expected ratio (o/e) 0.95, 90% interval 0.9 to 1.01. Synonymous variants: 379 observed, 365.24 expected, observed/expected ratio (o/e) 1.04, 90% interval 0.95 to 1.13.
Homologues: Orthologues: chimpanzee ATXN1L (99% identical), macaque ATXN1L (96% identical), dog ATXN1L (96% identical), pig ATXN1L (94% identical), guinea pig ATXN1L (94% identical), mouse Atxn1l (94% identical), rabbit ATXN1L (92% identical), rat Atxn1l (91% identical), tropical clawed frog atxn1l (52% identical), zebrafish atxn1l (43% identical), Caenorhabditis elegans K04F10.1 (12% identical), Drosophila melanogaster Atx-1 (11% identical). Paralogues in human: ATXN1 (30% identical).
Diseases named in the same sentence as ATXN1L in open-access papers:
ATXN1L is named in the same sentence as 15 diseases in open-access papers, as found by Europe PMC text mining. Sharing a sentence is not in itself a finding about the gene and the disease. The quoted sentences say what the papers report.
Ataxia (2 papers, 2012 to 2013). Ataxia refers to impaired coordination of voluntary muscle movement. "Our finding that Atxn1L, a gene identified from the Ataxia interactome, has a hematopoietic phenotype when ablated supports this concept." (PMID 23555280, 2013).
breast carcinoma (1 paper, 2020). "Degradation of CIC protein following loss of ATXN1L was instead observed to be mediated by the E3 ubiquitin ligase TRIM25 which was further validated using glioma-derived cell lines and the TCGA breast carcinoma and liver hepatocellular carcinoma cohorts." (PMID 33115448, 2020).
glioma (1 paper, 2020). A benign or malignant brain and spinal cord tumor that arises from glial cells (astrocytes, oligodendrocytes, ependymal cells). "Conversely, dysregulation of CIC through loss of ATXN1L has been observed in several other cancer subtypes including low-grade glioma and prostate, stomach, pancreatic, gastric, and lung adenocarcinomas." (PMID 33115448, 2020).
sarcoma (1 paper, 2022). A usually aggressive malignant neoplasm of the soft tissue or bone. "In summary, we report three aggressive undifferentiated sarcomas in infants or very young children with novel ATXN1/ATXN1L-associated fusions and gene-expression and methylation patterns similar to that of CIC-rearranged sarcomas." (PMID 35836290, 2022). "These three cases with novel ATXN1/ATXN1L-associated fusions and features of CIC-rearranged sarcomas may further expand the scope of “CIC-rearranged” sarcomas to include non-CIC rearrangements." (PMID 35836290, 2022).
spinocerebellar ataxia type 1 (1 paper, 2013). Spinocerebellar ataxia type 1 (SCA1) is a subtype of type I autosomal dominant cerebellar ataxia (ADCA type I) characterized by dysarthria, writing difficulties, limb ataxia, and commonly nystagmus and saccadic abnormalities. "Atxn1L is a paralog of ATXN1 (aka ATAXIN1), originally identified in humans as the gene mutated in Spinocerebellar ataxia type 1 (SCA1)." (PMID 23555280, 2013).
cancer (3 papers, 2019 to 2021). A tumor composed of atypical neoplastic, often pleomorphic cells that invade other tissues. "In fact, loss of CIC or ATXN1L modulates sensitivity to MEK inhibition in RAS-mutant cancers." (PMID 31242922, 2019). "ATXN1L is a member of the Ataxin protein family which has been shown to be a potent regulator of CIC function in both development and cancer." (PMID 33115448, 2020).
ATXN1L also shares sentences with these, for which no sentence is quoted: Aminoaciduria (1 paper); Anxiety (1); colon cancer (1); colorectal cancer (1); dentatorubral-pallidoluysian atrophy (1); pancreatic adenocarcinoma (1); spinobulbar muscular atrophy (1); tumor (1); viral infection (1).